DENND4C (DENN domain containing 4C)
Description:
Guanine nucleotide exchange factor (GEF) activating RAB10. Promotes the exchange of GDP to GTP, converting inactive GDP-bound RAB10 into its active GTP-bound form. Thereby, stimulates SLC2A4/GLUT4 glucose transporter-enriched vesicles delivery to the plasma membrane in response to insulin.
Synonyms: C9orf55; C9orf55B; FLJ20686; bA513M16.3; RAB10GEF
Tractability: Antibody: UniProt places it where antibodies can reach, with medium confidence; its Gene Ontology location is reachable by antibodies, with medium confidence. PROTAC: ubiquitination databases record sites on it; its protein half-life has been measured.
Gene: Protein-coding gene on chromosome 9 (19,230,435 to 19,374,281, forward strand). Ensembl gene ENSG00000137145.
Subcellular location: Cytoplasmic vesicle membrane; Cell membrane; Cytoplasm, cytosol
Subcellular location (Human Protein Atlas): Cytosol; Golgi apparatus; Vesicles
Pathways (Reactome):
Vesicle-mediated transport: RAB GEFs exchange GTP for GDP on RABs
Gene Ontology:
Molecular function: guanyl-nucleotide exchange factor activity
Biological process: cellular response to insulin stimulus; protein localization to plasma membrane; regulation of Rab protein signal transduction
Cellular component: cytosol; Golgi apparatus; insulin-responsive compartment; plasma membrane; cytoplasmic vesicle membrane
Genetic constraint (gnomAD): Loss-of-function variants: 89 observed, 180.01 expected, observed/expected ratio (o/e) 0.49, 90% interval 0.42 to 0.59. The upper end of that interval is the gene's LOEUF score, 0.59, which puts it in group 2 of 6, group 1 being the genes least tolerant of losing a copy. Missense variants: 2,375 observed, 2,278.7 expected, observed/expected ratio (o/e) 1.04, 90% interval 1.01 to 1.08. Synonymous variants: 843 observed, 785.17 expected, observed/expected ratio (o/e) 1.07, 90% interval 1.01 to 1.14.
Homologues: Orthologues: chimpanzee DENND4C (99% identical), macaque DENND4C (98% identical), pig DENND4C (92% identical), dog DENND4C (92% identical), rabbit DENND4C (91% identical), rat Dennd4c (88% identical), guinea pig DENND4C (88% identical), mouse Dennd4c (87% identical), tropical clawed frog dennd4c (68% identical), zebrafish dennd4c (62% identical), Drosophila melanogaster Crag (31% identical), Caenorhabditis elegans denn-4 (29% identical). Paralogues in human: DENND4A (48% identical), DENND4B (34% identical), DENND3 (12% identical).
Diseases named in the same sentence as DENND4C in open-access papers:
DENND4C is named in the same sentence as 7 diseases in open-access papers, as found by Europe PMC text mining. Sharing a sentence is not in itself a finding about the gene and the disease. The quoted sentences say what the papers report.
Allergy (1 paper, 2017). An allergy is an immune response or reaction to substances that are usually not harmful. "However, nonsynonymous mutations were identified in the coding sequences of Cer1, Ttc39b, Ccdc171, Cntln, Adamtsl1, Haus6, Gm12551, and Dennd4c, but these genes do not have any prior documented associations with allergy, IgE, or asthma." (PMID 28696925, 2017).
breast carcinoma (1 paper, 2023). "Circ-DENND4C (DENN domain containing 4C) has been shown to be overexpressed in breast cancer and glioma." (PMID 37546393, 2023).
tumor (1 paper, 2024). "Upon analyzing the expression of 11 model genes in prostate PRAD, we observed significant differential expression of eight genes (MYADM, MPDZ, LTBP2, DENND4C, PROK1, DDIT4, IGFBP3, and CFD) between normal and tumor tissues." (PMID 38898043, 2024).
DENND4C also shares sentences with these, for which no sentence is quoted: asthma (1 paper); epithelial ovarian cancer (1); glioma (1); infection (1).